INS (insulin)
Diseases named in the same sentence as INS in open-access papers (continued):
Sharing a sentence is not in itself a finding about the gene and the disease.
kidney stones (22 papers, 2015 to 2025). "Consistent with the IVW results of the replication stage, MR results successfully validated the significant association and similar direction of total triglycerides, fasting insulin, serum 25(OH)D, calcium, and urine pH with the risk of kidney stones." (PMID 37081554, 2023). "Interestingly, our MR results showed strong evidence for a positive association of fasting insulin with the incidence of kidney stones in both MR stages." (PMID 37081554, 2023). "Genetically predicted lower levels of caffeine consumption from tea, income, serum phosphorus, and urine pH, whereas higher levels of serum calcium, fasting insulin, and urinary sodium could increase the risk of kidney stones after FDR correction (FDR P < 0.05)." (PMID 37081554, 2023). "Thus, we considered that insulin levels and function might be more important than glycemia in increasing the risk of kidney stones." (PMID 37081554, 2023). "Relationship between insulin resistance indices and kidney stones in the logistic regression models." (PMID 40275575, 2025). "Relationship between insulin resistance indices and kidney stone recurrence in the logistic regression models." (PMID 40275575, 2025). "This study provides new insights into the mechanisms of insulin resistance in kidney stone formation and highlights the importance of individualized risk assessment." (PMID 40275575, 2025). "For per SD increase in serum calcium, fasting insulin, and urinary sodium, the ORs (95%CIs) of kidney stones were 1.21 (1.13, 1.29), 2.38 (1.34, 4.22), and 3.46 (1.59, 7.53), respectively." (PMID 37081554, 2023). "In addition, genetically predicted higher levels of waist-to-hip ratio adjusted body mass index (WHRadjBMI), fasting insulin, serum 25(OH)D, and serum calcium, whereas lower levels of years of education, and urine pH could elevate nephrolithiasis risk after FDR correction (FDR P < 0.05)." (PMID 37081554, 2023). "Baseline kidney stones were significantly associated with a higher level of LDL cholesterol, fasting insulin and HOMA_IR, which are cardio-risk factors, and a lower level of HDL cholesterol." (PMID 35958421, 2022). "These mediators may offer insight into the role of oxidative stress in linking insulin resistance to kidney stone formation." (PMID 40729360, 2025). "ROC test of six alternative insulin resistance indicators for kidney stones." (PMID 40729360, 2025). "Moreover, when patients with kidney stones become more insulin sensitive, urine oxalate excretion decreases." (PMID 35851836, 2022). "In the non-diabetic population, the insulin resistance index may represent an under-appreciated risk factor for kidney stones." (PMID 40275575, 2025). "The patient was initiated on insulin therapy since her diagnosis and presents no complications of DM; she reports nephrolithiasis." (PMID 35592779, 2022).
metabolic acidosis (22 papers, 2016 to 2026). "Metabolic acidosis may also result from a defect in proximal tubule ammonia synthesis, which may be caused by insulin resistance." (PMID 33261165, 2020). "Metabolic acidosis progresses as renal function declines and can adversely impact bone mineralization, skeletal muscle homeostasis, and insulin sensitivity while accelerating renal deterioration." (PMID 40871676, 2025). "Metabolic acidosis, defined as a blood pH < 7.35 and serum bicarbonate < 22 mmol/L, has clear pathophysiologic consequences including an effect on insulin action." (PMID 38473990, 2024). "Metabolic acidosis is a complication of CKD associated with increased protein catabolism, branched-chain amino-acids oxidation, reduced insulin sensitivity, and bone demineralization." (PMID 31598912, 2019). "Hence, therapy for metabolic acidosis was started in accordance with the department for endocrinology, including IV fluids (IVFs), IV continuous insulin (0.5 ml per hour with short-acting insulin), potassium substitution, and 5%-glucose solution." (PMID 35402477, 2022). "It is a heterogeneous and complex biochemical disorder characterized by the dysregulated insulin secretion from pancreatic β-cell causing random HY associated with low/normal ketones and absence of metabolic acidosis." (PMID 34408725, 2021). "A manifestation of metabolic acidosis can be suppressed by promoting anabolism and provides an alternative source of energy by an intravenously supplied dextrose, with or without insulin." (PMID 29678161, 2018). "Moreover, the likelihood is that dietary CP reductions have the potential to elevate circulating NH3 concentrations and promote metabolic acidosis and, importantly, both elevated plasma NH3 concentrations and metabolic acidosis can negatively influence insulin secretion and insulin sensitivity." (PMID 41437079, 2025).
pancreatic disease (22 papers, 2016 to 2026). "The algorithms applied were based on the results of insulin sensitivity and insulin secretion, as well as on a pancreatic polypeptide, a parameter correlated with the development of several pancreatic diseases including endocrine tumors." (PMID 40299428, 2025). "Collectively, UCP2 plays a crucial role in regulating energy homeostasis, ROS, insulin secretion, and overall metabolism, influencing the progression of pancreatic diseases and β-cell function via pathways including AMPK, Wnt, and NF-κB." (PMID 39707176, 2024). "Dysregulation of RPN2 and its associated pathways can contribute to the development of various pancreatic diseases via defective insulin production, impacting glucose homeostasis." (PMID 39000422, 2024). "Several studies have confirmed the potentially critical role of PPARs in pancreatic diseases, including protecting pancreatic islet β-cells from metabolic stress, enhancing insulin secretion, and mitigating lipotoxicity." (PMID 39707176, 2024). "This is a neoplastic pancreatic disease defined by the presence of multiple small and large insulin-producing tumors which develop simultaneously or metachronously." (PMID 35838801, 2022). "Furthermore, ncRNAs are vital regulators of pancreatic diseases, influencing inflammation, fibrosis, insulin secretion, and cell survival.In this section, we summarize the ncRNAs involved in the epigenetic regulation of UCP2." (PMID 39707176, 2024). "Conversely, people with T1DM (as well as subjects who undergo total pancreatectomy or with severe pancreatic disease) totally depend on exogenous insulin administration, which arrives to the liver and to peripheral tissues simultaneously and at a similar concentration." (PMID 35681699, 2022). "Other studies showed that offspring consumption of a rich carbohydrate-milk during lactation increased plasma levels of INS and LEP, and also BW, resulting in pancreatic disorders." (PMID 27011203, 2016).
Acidosis (21 papers, 2010 to 2025). Abnormal acid accumulation or depletion of base. "When a child is diagnosed with DKA, initial management is particularly labour-intensive and requires intravenous insulin infusion, hourly glucose and ketone checks and frequent venous gas analyses to monitor the associated acidosis." (PMID 40481412, 2025). "Acidosis in the insulin-treated group was lower than the control group, but the difference was minimal and was most likely caused by the catabolic effect of insulin." (PMID 25278226, 2014). "Persons with metabolic acidosis showing larger anion gap associated with lower serum HCO3− indicate less insulin sensitivity (higher insulin resistance): low serum HCO3− means that the body produces a large amount of H+, which would consume serum HCO3− for pH homeostasis." (PMID 30347717, 2018). "Acidosis also increases the urinary excretion of calcium and magnesium that play important roles in insulin action." (PMID 32486113, 2020). "Metabolic acidosis reduces the binding of insulin to its receptors in isolated adipocytes, alters the intracellular insulin signaling pathway, and increases production of the anti-insular hormone cortisol." (PMID 29762478, 2018). "Acidosis, due to its effects on insulin-regulated pathways, may increase proteolysis, lipolysis and inhibit cell growth and proliferation." (PMID 38473990, 2024). "Findings which propose an active role of diet-induced acidosis in the regulation of insulin sensitivity are in accordance with experimental data showing that in models of metabolic acidosis, such as end-stage kidney failure, insulin sensitivity can be restored via alkali supplementation." (PMID 29762478, 2018). "Acidosis thus has the potential to directly affect the insulin-stimulated glucose uptake by interfering with the first step of the insulin signaling pathway, the IR activation, which, as a consequence, might impair the downstream IR signaling." (PMID 30598026, 2018). "However, few lines of evidence also suggest that metabolic acidosis, that commonly complicates CKD, is implicated in suboptimal biological responses to insulin." (PMID 27770799, 2016). "Acidosis induces the transcription and expression of Transforming Growth Factor (TGF)-β, which inhibits insulin secretion and reduces the affinity of insulin to its receptor." (PMID 32486113, 2020). "Indeed, metabolic acidosis, which is a common complication of severe CKD, is a major factor promoting insulin resistance, which in turn may lead to fat accumulation in the muscles." (PMID 40304205, 2025).
anovulation (21 papers, 2011 to 2025). The absence of ovulation. "Such an association between elevated circulating insulin levels and anovulation is of particular note, since PCOS-like monkeys exhibit many of the reproductive and metabolic defects found in women with PCOS, implying a fetal origin for the syndrome." (PMID 35269778, 2022). "Type II classic (anovulation and hyperandrogenism) is nearly as severe as Type I and shares the increased risk for metabolic dysfunction and insulin insensitivity." (PMID 31367382, 2019). "Although insulin sensitizers are reportedly effective against anovulation associated with PCOS or for suppression of excessive follicular growth, the underlying mechanism of action remains unknown." (PMID 31472696, 2019). "Treatment with insulin sensitizers is reportedly effective for both anovulation associated with PCOS, and suppression of excessive follicular growth; however, the underlying mechanism of action remains unknown." (PMID 31472696, 2019). "INS was also associated with anovulation in PCOS, although there are conflicting studies." (PMID 26308735, 2015). "Conversely, PCOS-like female monkeys with normal circulating insulin levels exhibit only 21% incidence of anovulation, outside summer months of oligomenorrhea in this seasonally breeding species." (PMID 35269778, 2022). "Participants were between 18 and 31 years old with anovulation (the menstrual cycle was delayed by 3 months–3 years) and normotensive but mainly insulin resistant (patients at the beginning of the study had a HOMA-IR higher than 2.3)." (PMID 33849562, 2021). "Since androgens are considered the main source of PCOS, and androgenization of animals is the most frequently used approach to induce PCOS, of which characteristics include anovulation, cyst-like follicles, elevated LH levels, increased adiposity, and insulin insensitivity." (PMID 36159582, 2022). "High levels of insulin lead to high levels of IGF-1 and androgens, resulting in anovulation." (PMID 38671840, 2024). "It has been suggested that higher levels of insulin, LH, and androgens increase the concentration of VEGF, leading to abnormally increased vascularity in the ovary, which may exacerbate anovulation and subfertility." (PMID 33424968, 2020).
autism (21 papers, 2015 to 2025). Persistent deficits in social interaction and communication and interaction as well as a markedly restricted repertoire of activity and interest as well as repetitive patterns of behavior. "An upregulation of the PI3K/Tor pathway, a key intracellular mediator of insulin signaling, is associated with the onset of autism." (PMID 39329976, 2024). "This study seeks to explore the potential therapeutic benefits of IN insulin in a rat model of autism induced by PPA." (PMID 39329976, 2024). "Following insulin administration, a substantial reduction in autism symptoms was observed in all three social behavior tests conducted on the rats." (PMID 39329976, 2024). "Insulin administration via IN alleviates autism-like behavioral, biochemical, and histopathological alterations induced by PPA in rats through modulation of signaling and anti-inflammatory pathways." (PMID 39329976, 2024). "This study is the first and only research that quantitatively assesses the physiological impacts of intranasal insulin administration in a rat model of autism induced by PPA." (PMID 39329976, 2024). "The administration of insulin via IN exhibits alleviating effects on autism-like behavioral, biochemical, and histopathological alterations induced by PPA in rats." (PMID 39329976, 2024). "The results here provide consistency with the observation that external administration of insulin can reduce autism symptoms." (PMID 39329976, 2024). "Biomarkers linked to autism and/or pioglitazone were also studied to attempt to understand the mechanisms involved, namely, IL-6, TNF-alpha, MCP-1, insulin, and leptin." (PMID 29791472, 2018). "Neuroimmune biomarkers linked to autism and/or pioglitazone, namely, IL-6, tumor necrosis factor (TNF)-alpha, monocyte chemotactic protein (MCP)-1/CCL2, insulin, and leptin, were also studied." (PMID 29791472, 2018). "Additionally, our findings show an association between the miR-1228-3p target genes and the insulin signaling pathway, which are hypothesized to contribute to the development of autism in genetically susceptible individuals by promoting PI3K/Tor pathway activation in neurons." (PMID 26061495, 2015). "Thirty male Wistar albino rats were categorized into three cohorts: the control group, the PPA-induced autism (250 mg/kg/day intraperitoneal PPA dosage for five days) group, treated with saline via IN, and the PPA-induced autism group, treated with 25 U/kg/day (250 μL/kg/day) insulin via IN." (PMID 39329976, 2024). "According to the previous evidence, abnormal secretion of some hormones, such as adiponectin, leptin, ghrelin, insulin, and IGF-1 may cause changes in the growth process, especially in early life, and may be associated with the risk of autism." (PMID 38066466, 2023). "Insulin signaling pathway is feasible for development of autism." (PMID 36750796, 2023). "The insulin analyses were performed because of their relation with both pioglitazone and autism." (PMID 29791472, 2018). "What we found at the gene set level may also be consistent with prior findings of enhanced insulin signaling in the brain of a Drosophila model of Fragile X syndrome, which represents the most prevalent hereditary type of intellectual disability and autism." (PMID 35165256, 2022). "Interestingly, this study found that insulin therapy given to diabetic rats appeared to counteract these pathophysiological mechanisms induced in the offspring, suggesting that insulin therapy during pregnancy may prevent autism-like behavior." (PMID 37469977, 2023). "Moreover, insulin exhibited noteworthy capabilities in decreasing brain MDA, IL-2, IL-17, and TNF-α levels within autism models." (PMID 39329976, 2024). "Interestingly, the approach to use insulin-sensitizing drugs for affected subjects with autism is not new and it was shown in a mouse model of autism that Metformin showed positive effects on social behavior in C57/BL6 mice." (PMID 35743898, 2022).
autoimmune type 1 diabetes (21 papers, 2008 to 2025). Autoimmune disease wherein the body's own immune system attacks and destroys the cells within the pancreas that produce insulin. "For diagnostic evaluation, it is important that the endogenous insulin secretion is evaluated by C-peptide levels and anti-islet autoantibodies, with approximately 95% of cases classified as autoimmune type 1 diabetes." (PMID 40650275, 2025). "Autoimmune type 1 diabetes is characterised by the progressive loss of insulin-producing beta cell mass and, eventually, insufficient insulin to maintain blood glucose levels within normal ranges." (PMID 38864887, 2024). "Autoimmune Type 1 diabetes, also known as juvenile-onset diabetes, is caused by a person's own immune system mistakenly destroying their insulin-producing cells in the pancreas, known as beta cells, which produce insulin in response to food intake to control the level of blood sugar." (PMID 23355961, 2011). "A hydrogel of Nap‐GdFdFdY containing conserved sequence of autoantigens including insulin, proinsulin, and glutamic acid decarboxylase as a novel therapeutic intervention for the autoimmune type 1 diabetes." (PMID 34026440, 2021). "The possible effect of insulin treatment as a trigger or accelerator of autoimmune (type 1) diabetes needs further exploration." (PMID 22567309, 2012). "Autoimmune type 1 diabetes (T1D) development results from the interaction between pancreatic β-cells, and the innate and the adaptive immune systems culminating with the destruction of the insulin-secreting β-cells by autoreactive T cells." (PMID 24968718, 2014). "Both plasma insulin as well as serum C-peptide levels are not low, although inadequate for the respective glucose levels, and autoantibodies related to autoimmune type 1 diabetes are negative." (PMID 39408828, 2024). "In this context, autologous grafting of the fused cells derived from individuals or cells that are engineered to express active insulin into the pancreas of the NOD mice, a polygenic model for autoimmune type 1 diabetes, may be of interest for future trials." (PMID 28767080, 2017). "In the non-obese diabetic (NOD) model of autoimmune Type 1 diabetes (T1D), Hpse is also used by insulitis leukocytes to solubilize the islet BM to enable intra-islet entry of leukocytes and to degrade intracellular HS, an essential component for the survival of insulin-producing islet beta cells." (PMID 24421779, 2013). "It is therefore possible that the N-terminal GAD65-restricted GADA, as proposed, does not detect individuals with autoimmune type 1 diabetes, at least using clinical phenotype as a proxy, whilst screening for t-GADA could be helpful for clinical assessment and prediction of insulin therapy." (PMID 29619531, 2018).
multiple sclerosis (21 papers, 2009 to 2025). A progressive autoimmune disorder affecting the central nervous system resulting in demyelination. "These beneficial effects include the counteractions of traumatic brain injury and severe encephalopathies after NSAID overdose, insulin overdose, magnesium overdose, and exposure to the neurotoxin cuprizone in a rat model of multiple sclerosis." (PMID 31266512, 2019). "The most common consistent self-management behavior was taking long term medications (e.g., anti-rheumatic drugs, blood pressure medications, insulin, multiple sclerosis-modifying treatments)." (PMID 23647658, 2013). "Relatedly, in our small study, we also found “insulin secretion” was an enriched KEGG pathway, further tying glucose metabolism and multiple sclerosis." (PMID 38880880, 2024). "One such compound may be the multiple sclerosis drug, FTY720, which like aSyn can stimulate the activity of the catalytic subunit of protein phosphatase 2A (PP2Ac) as well as insulin secretion." (PMID 30622456, 2018).